MANF (mesencephalic astrocyte derived neurotrophic factor)
Diseases named in the same sentence as MANF in open-access papers (continued):
Sharing a sentence is not in itself a finding about the gene and the disease.
Obesity (15 papers, 2017 to 2025). Accumulation of substantial excess body fat. "The fact that MANF is highly enriched in the hypothalamus and transgenic MANF causes obesity in MANF transgenic mice leads us to propose MANF functions in the hypothalamus to regulate energy homeostasis." (PMID 28924165, 2017). "In addition, in a clinical exome sequencing screen a homozygote missense mutation in the MANF gene indicative of deficient MANF expression was found in a patient suffering from Type 2 diabetes and obesity, short stature, microcephaly, and other anomalies." (PMID 31781038, 2019). "However, whether MANF is involved in the diabetic phenotype caused by paternal obesity is yet unclear." (PMID 40041941, 2025). "Our study links EZH2‐H3K27me3 with the decrease of MANF and provides a direction for finding effective therapeutic strategies for treating the paternal obesity‐induced transgenerational glucose metabolic dysfunction." (PMID 40041941, 2025). "The liver-specific overexpression of MANF reduces HFD-induced obesity by promoting inguinal white AT browning and thermogenesis." (PMID 35909571, 2022). "The feeding-induced mesencephalic astrocyte-derived neurotrophic factor was recently shown to ameliorate diet-induced obesity by promoting adipose browning." (PMID 35462937, 2022). "Further studies are required to identify the receptor of MANF and to explore the mechanisms contributing to MANF elevations in patients with obesity." (PMID 35909571, 2022). "A recent study identified MANF as a hepatokine induced by feeding and revealed its potential role in energy homeostasis and obesity." (PMID 35909571, 2022). "A recent study showed that MANF protected mice against high-fat diet–induced obesity by promoting adipose browning via p38 MAPK pathway." (PMID 35110525, 2022). "In a recent study, increased expression of MANF in hypothalamic neurons of mice led to increased feeding behavior and obesity, whereas reduced expression specifically in hypothalamic neurons led to hypophagia and reduced body weight." (PMID 31781038, 2019). "Another recent study suggested that MANF can regulate energy homeostasis, as transgenic overexpression of MANF in the brain hypothalamus led to overfeeding and obesity in mice." (PMID 31586115, 2019). "Interestingly, an exome sequencing study identified MANF as a potential causative gene for a 22-year-old woman patient with type 2 diabetes mellitus, hypothyroidism, primary hypogonadism, short stature, mild intellectual disability, obesity, deafness, high myopia, microcephaly and partial alopecia." (PMID 30555354, 2018). "More clinical data are needed to firmly establish the link between MANF and obesity development in human." (PMID 30555354, 2018). "Increasing MANF expression in the hypothalamus lead to the development of hyperphagia and obesity, whereas reducing MANF expression in the hypothalamus leads to hypophagia and retarded body weight gain." (PMID 28924165, 2017). "The latest research demonstrated that hepatocyte-derived MANF plays a crucial role in increasing insulin sensitivity and that the systemic injection of MANF protein greatly enhanced insulin sensitivity in mice exhibiting obesity." (PMID 36936164, 2023). "Similarly, among the 15 anti-inflammatory organokines, 7 (adiponectin, Omentin-1, ZAG, SFRP5, CTRP3, IL-10, and DEL-1) showed reduced levels and 8 (LCN2, VASPIN, IL-1RA, FGF21, GDF15, MANF, Irisin, and IL-6) showed elevated levels in patients with obesity." (PMID 35909571, 2022). "Notably, the intravenous injection of recombinant MANF-Fc reduces obesity and related metabolic abnormalities by increasing thermogenesis in both HFD-induced and ob/ob obese mouse models." (PMID 35909571, 2022). "Of note, circulating MANF levels were found to be positively correlated with BMI in humans, indicating that obesity may increase the peripheral level of MANF in a compensator manner to relieve excessive weight gain." (PMID 36031641, 2022).
Obesity (continued). "This suggests that MANF is an anti-obesity hepatokine and that elevated serum levels of MANF could represent a compensatory effect occurring in response to overweight." (PMID 35909571, 2022). "It remains unknown whether MANF is up-regulated under chronic ER stress conditions, such as during the development of obesity." (PMID 30555354, 2018). "Altered function of MANF could have a significant impact on energy homeostasis, which potentially leads to obesity and other metabolic disorders." (PMID 28924165, 2017). "Therefore, increasing MANF level in the hypothalamus leads to an impaired insulin response, which results in hyperphagia and obesity." (PMID 28924165, 2017). "Furthermore, liver-specific MANF ablation impaires white AT browning and worsens obesity." (PMID 35909571, 2022). "Overexpressed MANF was suggested to recruit and activate PIP4k2b in the ER, thus reducing AKT phosphorylation downstream of insulin receptor signaling leading to hyperphagia and obesity." (PMID 30386256, 2018).
ischemia (14 papers, 2012 to 2024). A hypoperfusion of the BLOOD through an organ or tissue caused by a PATHOLOGIC CONSTRICTION or obstruction of its BLOOD VESSELS, or an absence of BLOOD CIRCULATION. "The results suggest that upregulated MANF expression is associated with activated glial cells, which will help us to understand the function of MANF and the mechanisms of ischemia-induced neural injury." (PMID 23173607, 2012). "When we overexpressed the MANF transgene in the rat cortex before cortical stroke induction by distal MCAo (dMCAo), the expression pattern of transduced MANF was changed 6 h after ischemia, causing redistribution of MANF from the cell soma to the processes of neurons and glia." (PMID 35783104, 2022). "Administration of rMANF before ischemia improved myocardial function and reduced infarct area to some extent, highlighting the protective role of MANF as an ER stress-induced secreted cardiomyokine." (PMID 39242993, 2024). "We observed some MANF positive microglial cells in the contralateral hemisphere of rat brains, but it seems that translation of MANF protein is strongly induced after ischemia in activated microglia/macrophages." (PMID 38229173, 2024). "The multifaceted neuroprotection offered by MANF underscores its potential as a promising avenue for further research in neurodegenerative diseases and ischemia-related conditions." (PMID 37751132, 2023). "The previous researches have reported that MANF expression in glial cells is enhanced under the condition of focal cerebral ischemia; also, ischemia in heart is able to induce MANF expression as well." (PMID 35911675, 2022). "AAV-induced MANF expression was also observed in neurons and glia of the cerebral cortex following ischemia." (PMID 33994992, 2021). "The ability of DHA to regulate expression of MANF following ischemia implies a possible mechanism by which DHA is able to protect against further cell and tissue damage." (PMID 32757264, 2020). "In our previous study, we intracerebroventricularlly (icv) injected recombinant human MANF protein to the MCAO rats after 2 h of MCAO and found that MANF protein improved the behavior of ischemia rats and promoted the survival of the neuron." (PMID 27608005, 2016). "Our data demonstrate that intracerebroventricular injection of MANF protein at 3 h after reperfusion can reduce the infarct volume, increase the survival rate after ischemia/reperfusion injury, and speed up the locomotor functional recovery." (PMID 27608005, 2016). "Here, we developed a magnetic resonance imaging (MRI) technology to dynamically evaluate the therapeutic effects of MANF on ischemia/reperfusion injury." (PMID 27608005, 2016). "Several studies about the protective effects of MANF on neuron lesion induced by ischemia have been recently reported." (PMID 27608005, 2016). "Our study found that ischemia and ER stress induced MANF expression in the oligodendrocytes, accompanied by a decrease in processes." (PMID 23173607, 2012). "In this study, we found that ischemia-induced MANF expression in microglia depends on the state of microglia." (PMID 23173607, 2012). "MANF offers diverse neuroprotection in neurodegenerative diseases and ischemia." (PMID 37751132, 2023). "Furthermore, we observed a punctate pattern of transduced MANF after ischemia, suggestive that the MANF protein is released from cells after ischemia or locally translated in axonal/dendritic processes." (PMID 35783104, 2022). "The cytoprotective effect of MANF against ischemia is not limited to neuronal cells, but the recombinant MANF protein reduced the myocardial infarct size in a mouse model of transient myocardial ischemia as well as reduced hypoxia-induced apoptosis in rat retinal ganglion cells in vivo and in vitro." (PMID 35783104, 2022).
ischemia (continued). "Our previous studies show that MANF protects against the neuron death induced by ischemia injury." (PMID 30760285, 2019). "MANF protein was upregulated in cortical neurons after cortical ischemia induced by MCAO in rats." (PMID 29966219, 2018). "MANF mRNA and protein were induced on ATF6 activation in the myocardium, in vivo, consistent with the hypothesis that ER stresses, such as ischemia, which can activate ATF6, a hallmark of ER stress genes, might also induce MANF expression in the heart." (PMID 28536652, 2017). "Meanwhile, we found that MANF is mostly expressed in neurons in the brains of APP/PS1 mice, which is in accordance with the characteristics of MANF expression in rat ischemia model." (PMID 30760285, 2019). "MANF expression was induced in MCAO rats at the early stage of ischemia, starting from 2 h of ischemia/2 h reperfusion." (PMID 29966219, 2018). "MANF protein decreased the mortality of MCAO rats within the early period of ischemic injury, and constantly lowered the ischemia lesion size shown by MRI images." (PMID 27608005, 2016). "Although MANF protein has not cured the ischemia/reperfusion injury completely, it relives the injury and reduces the lesion area, which may become a potential choice for the combined therapy of ischemia brain injury in the future." (PMID 27608005, 2016).
type 1 diabetes (13 papers, 2016 to 2025). "Increased MANF concentrations in serum are associated with the clinical manifestation of type 1 diabetes in children." (PMID 36830970, 2023). "In our study, we found that cultured human beta cells persistently expressed and secreted up to threefold more MANF when exposed to cytokines associated with the pathogenesis of type 1 diabetes." (PMID 30032427, 2018). "A recent discovery has linked MANF to the development of insulin-dependent diabetes in mice." (PMID 27356471, 2016). "In contrast, circulating MANF levels are known to increase in children with type 1 diabetes as compared with control subjects." (PMID 32366942, 2020). "We have shown that conventional MANF knock-out (KO) mice and pancreas-specific conditional KO mice develop insulin-dependent diabetes due to prolonged ER stress in pancreatic β cells, leading to loss of the β cell mass and premature death." (PMID 32005751, 2020). "Previous studies have shown increased circulating MANF concentrations in prediabetes and type 2 diabetes, and in children with recent onset of type 1 diabetes." (PMID 31555085, 2019). "Circulating MANF levels are increased in human children with recent onset of type 1 diabetes and in adults with prediabetes and type 2 diabetes, suggesting that alterations in levels of circulating MANF can indicate changes in energy metabolism." (PMID 31586115, 2019). "The current study aimed at determining whether the concentration of circulating MANF is associated with the clinical manifestation of human type 1 diabetes (T1D)." (PMID 27356471, 2016). "Furthermore, it has recently been shown that MANF levels are elevated in individuals newly diagnosed with type 1 diabetes." (PMID 30032427, 2018). "However, early-onset juvenile diabetes arises with the loss of MANF in mice and humans, but not in Atf6–/– mice, and has not been reported in patients carrying ATF6 loss-of-function variants." (PMID 39570676, 2025). "Thus, increased MANF levels in patients with type 1 diabetes may be an adaptive response to ER stress in β cells." (PMID 32366942, 2020). "Our data demonstrate that MANF mitigates inflammation and cell death by suppressing the NPTN-mediated inflammatory signal in a cell model of type 1 diabetes." (PMID 33299977, 2020).
ischemic stroke (11 papers, 2018 to 2024). A stroke disorder caused by obstruction of blood flow to the brain, due to thrombotic (local blood clot formation) or embolic (due to a blood clot or other material traveling from another site) event. "We have previously shown that viral-vector mediated overexpression of MANF in the peri-infarct region increases the number of phagocytic microglia/macrophages after ischemic stroke and downregulates proteins S100A8 and S100A9 related to innate immunity." (PMID 38229173, 2024). "Administration of recombinant MANF into mouse brain has been shown to downregulate inflammation by decreasing NF-κB-mediated pro-inflammatory cytokine production in vivo in an ischemic stroke model in aged mice and in vitro after oxygen–glucose deprivation." (PMID 38229173, 2024). "MANF is considered a protective molecule in several neurological diseases, including PD, ischemic stroke, and retinal degeneration." (PMID 39425207, 2024). "During the first days after ischemic stroke, MANF protein expression was decreased in the infarct core in both patients and rodents." (PMID 38229173, 2024). "Systemic administration of MANF presents a novel therapeutic approach to utilize these cytoprotective and anti-inflammatory properties in ischemic stroke." (PMID 38229173, 2024). "We aimed to investigate how endogenous cerebral MANF protein expression evolves in infarcted human brains and rodent ischemic stroke models." (PMID 38229173, 2024). "There was an obvious enhancement of serum levels of MANF in both humans and rats with ischemic stroke." (PMID 37268902, 2023). "MANF can inhibit apoptosis/necrosis in the ischemic brain, and the CxxC-motif is indispensable for the neuroprotective effect of MANF in ischemic stroke, possibly because of its importance in maintaining MANF’s structural conformation." (PMID 35783104, 2022). "Immune cell activation after ischemic stroke or systemic LPS has been shown to upregulate MANF in microglia." (PMID 35783104, 2022). "Intracerebral administration of MANF 2 days following ischemic stroke increased the quantity of phagocytic microglia at 4 days in the peri‐infarct region, and rhMANF promoted neuron proliferation and prevented neuronal apoptosis." (PMID 32757264, 2020). "Moreover, systemic delivery of recombinant MANF shows promising immunomodulatory effects and therapeutic potential in experimental ischemic stroke." (PMID 38229173, 2024). "Furthermore, MANF has been shown to increase the pro-regenerative and anti-inflammatory activation, known as alternative activation, of innate immune cells in an ischemic stroke model and the damaged retina of mouse and fruit fly." (PMID 38229173, 2024). "We then studied whether we observe a similar expression pattern in rodent models of ischemic stroke, and identified which cells express MANF protein." (PMID 38229173, 2024). "We hypothesize that when MANF is released from injured cells upon ER Ca2+ depletion, the released MANF could modulate the immune cell phenotype and, in ischemic stroke, the recruitment of phagocytic cells to the area of injury." (PMID 35783104, 2022). "However, in ischemic stroke, we have reported that MANF induced a transient increase in CD68-positive innate immune cells, which is likely beneficial for tissue repair." (PMID 35783104, 2022). "However, studies on post-ischemic MANF expression have focused on acute time-points, and a thorough long-term study on MANF expression after ischemic stroke in animal models and in ischemic stroke post-mortem patient samples is further warranted." (PMID 35783104, 2022). "MANF levels are known to be disturbed in neurodegenerative diseases or ischemic stroke." (PMID 36585419, 2022). "Besides, it was reported that the protein level of MANF was highly elevated in traumatic brain injury and ischemic stroke." (PMID 29896089, 2018).
ischemic stroke (continued). "Intracranial delivery of MANF is neuroprotective but not feasible in ischemic stroke patients due to increased risk of hemorrhage caused by thrombolytic treatment and the infarct itself, and therefore it is vital to explore the possibility for non-invasive delivery." (PMID 38229173, 2024). "Mesencephalic astrocyte-derived neurotrophic factor (MANF) has been originally described as a neurotrophic factor but has subsequently been found to be an important regulator of endoplasmic reticulum (ER) lumen homeostasis and to have a protective effect on ischemic stroke outcome." (PMID 35783104, 2022). "Docosahexaenoic acid (DHA) treatment enhances mesencephalic astrocyte-derived neurotrophic factor (MANF), reduces the expression of TREM2 and ischemic brain damage, activates neurogenesis, and promotes functional recovery after experimental ischemic stroke." (PMID 36212660, 2022). "MANF and XBP1 are both detected right after ischemic stroke, and their expression is still elevated even 2 weeks after the injury." (PMID 35783104, 2022). "MANF expression colocalized with GRP78 in CD68-positive cells, indicating UPR activation in microglia/macrophages after ischemic stroke." (PMID 35783104, 2022). "As the intracranial delivery of MANF has been shown to be neuroprotective in ischemic stroke models, we conducted a proof-of-concept study using non-invasive intranasal delivery of rhMANF." (PMID 38229173, 2024). "It should be noted that MANF’s protective activity by gene therapy in vitro was abolished with the deletion of the C-terminal RTDL domain, but the protein was biologically active and showed protective effects on ischemic stroke in vivo." (PMID 35783104, 2022). "Moreover, we demonstrated that DHA treatment enhanced MANF, decreased TREM2 expression, reduced ischemic brain injury, activated neurogenesis, and promoted functional recovery after experimental ischemic stroke." (PMID 32757264, 2020). "Moreover, we suggest that MANF and TREM2 are an attractive target as a therapeutic avenue for ischemic stroke and other cerebrovascular diseases." (PMID 32757264, 2020). "To characterize MANF protein expression in the infarcted human brain, we utilized immunohistochemistry for MANF and CD68 in consecutive postmortem tissue sections of patients deceased approximately 3 days, 1 week and 2 weeks after ischemic stroke (n = 2–3 per time point)." (PMID 38229173, 2024). "Recent research has demonstrated that mesencephalic astrocyte derived neurotrophic factor (MANF) inhibits the production of proinflammatory factors and relies on the TLR4/MyD88/NF-B pathway to maintain the integrity of the blood-brain barrier in a geriatric mouse model following an ischemic stroke." (PMID 38020537, 2023). "However, MANF without the RTDL sequence is still protective in vivo in ischemic stroke, indicating that KDELRs are not necessary for mediating MANF’s neuroprotective effects in vivo." (PMID 35783104, 2022).